ICAM1 (intercellular adhesion molecule 1)
Diseases named in the same sentence as ICAM1 in open-access papers (continued):
Sharing a sentence is not in itself a finding about the gene and the disease.
chronic obstructive pulmonary disease (8 papers, 2015 to 2023). A chronic and progressive lung disorder characterized by the loss of elasticity of the bronchial tree and the air sacs, destruction of the air sacs wall, thickening of the bronchial wall, and mucous accumulation in the bronchial tree. "A recent study on chronic obstructive pulmonary disease revealed that, NOx levels correlate insignificantly with ICAM-1." (PMID 30577523, 2018). "ICAM-1 is also upregulated in fibrosis in chronic obstructive pulmonary disease (COPD), indicating its possible function in the enhancement of the immune response and promotion of fibrosis." (PMID 26368286, 2015). "As a marker for inflammation, ICAM-1 is increased in atherosclerosis, chronic obstructive pulmonary disease (COPD), sepsis, and age-related cognitive disorders." (PMID 35268306, 2022). "Furthermore, patients with chronic obstructive pulmonary disease (COPD) had higher plasma levels of ICAM-1 and IL-6 compared to healthy subjects." (PMID 29329563, 2018). "During pulmonary pathogenesis in chronic obstructive pulmonary disease (COPD), human NRP-1+ ILC3 located in proximity to blood vessels and lung ectopic lymphoid tissues, where they induced VCAM-1 and ICAM-1 expression on mesenchymal stromal cells, and efficiently responded to VEGF-A." (PMID 37234993, 2023).
emphysema (8 papers, 2014 to 2024). "In this case, higher soluble ICAM-1 was associated with a more rapid progression of emphysema." (PMID 35563159, 2022). "Furthermore, oral administration of the drug not only reduced the emphysema-associated lung lesions but also suppressed ICAM-1 protein and mRNA expression in the lungs compared with the control (all P<0.05 or 0.01)." (PMID 29789401, 2018). "Circulating biomarkers such as soluble intercellular adhesion molecule (ICAM-1), surfactant protein D and soluble receptor for advanced glycation end product (sRAGE) have also been shown to be higher in more rapid emphysema progressors." (PMID 27902753, 2016). "Validation in the TESRA cohort revealed significant associations with RAGE, ICAM1, and CCL20 with radiologic emphysema (p < 0.001 after meta-analysis)." (PMID 25306249, 2014). "Statistical analysis revealed a significant correlation between S100β and Hps70 immunoexpression and cerebral pathological features, between ICAM-1 immunoexpression and alveolar edema and pulmonary emphysema, and between AQP-1 immunoexpression and pulmonary emphysema." (PMID 38611652, 2024). "There is currently quite limited information about the association of ICAM1 to COPD and emphysema." (PMID 25306249, 2014). "In addition, intercellular adhesion molecule 1 (ICAM1), macrophage inhibitory protein 3a (CCL20) and cadherin 1 (CDH1) were negatively associated with emphysema severity." (PMID 25306249, 2014). "Regression analysis identified multiple biomarkers associated with CT-assessed emphysema in COPDGene, including advanced glycosylation end-products receptor (AGER or RAGE, p < 0.001), intercellular adhesion molecule 1 (ICAM, p < 0.001), and chemokine ligand 20 (CCL20, p < 0.001)." (PMID 25306249, 2014). "It should be noted that ICAM-1 may play an important role in the pathogenesis of emphysema." (PMID 35563159, 2022). "The study confirms a previously identified association between radiologic emphysema and sRAGE, builds on data suggesting a role for ICAM1 as a biomarker, in addition to discovering previously not identified biomarkers associated with emphysema such as CCL20, cadherin 1, cadherin 13 and SERPINA7." (PMID 25306249, 2014). "Other studies relate ICAM1 levels to active smoking and preliminary analysis from The MESA Lung Study demonstrated that ICAM1 predicted 0.15%/year increase in CT-assessed emphysema, suggesting a role for this molecule as a biomarker of emphysema and that it may play a role in emphysema pathogenesis." (PMID 25306249, 2014). "ICAM-1 gene was up-regulated in COPD patients, whereas the increase in the gene expression was related to sustained recruitment of neutrophils into the inflamed airway tissue, which in turn led to structural destruction in emphysema." (PMID 29789401, 2018). "In the present study, we found decreased ICAM1 levels correlate with increased severity of emphysema on CT scan, independent of smoking status, FEV1 and other covariates." (PMID 25306249, 2014). "These biomarkers (AGER, ICAM1 and CCL20) were associated with emphysema regardless of quantification technique (%LAA ≤ −950 and ≤ −910 HU and LP15A) and were replicated in an independent COPD cohort (TESRA), thus strengthening their potential utility for defining clinically relevant emphysema." (PMID 25306249, 2014). "Our findings, particularly when combined with other studies of individual biomarkers, suggest that a panel of blood biomarkers including sRAGE, ICAM1 and CCL20 may serve as a useful surrogate measure of emphysema and may shed light on disease pathogenesis, providing targets for new treatments." (PMID 25306249, 2014). "Similarly, with regard to the LP15A emphysema outcome variable, meta-analysis with the TESRA cohort validated the association of RAGE (p = 2.5 × 10−10), ICAM1 (p = 6.0 × 10−11), and AXL (p = 3.8 × 10−3) with radiologic emphysema independent of covariates." (PMID 25306249, 2014).
falciparum malaria (8 papers, 2008 to 2025). "In our study, Ang-2 was also associated with ICAM-1 and E-selectin among patients with vivax malaria, consistent with the role of Ang-2 in activating endothelium in vivax as well as falciparum malaria." (PMID 25569250, 2015). "CD36 is not expressed on areas of brain endothelium where cytoadherence occurs and binding to ICAM-1 on brain endothelium is implicated in the pathophysiology of severe falciparum malaria with coma." (PMID 22305466, 2012). "In falciparum malaria TNF has been implicated in ICAM-1 up-regulation although infected red blood cells alone are sufficient to produce this effect." (PMID 22305466, 2012). "We have analysed the role of polymorphic variants of ICAM-1 in severe falciparum malaria using static and flow based adhesion assays and CD36 in static assays only." (PMID 21390226, 2011). "Intercellular adhesion molecule-1 (ICAM-1) is a cytoadhesion molecule implicated in the pathogenesis of Plasmodium falciparum malaria." (PMID 20712868, 2010). "The results indicate the significance of specific genetic variants of ICAM1, PECAM1 and CD36 in influencing the outcome of falciparum malaria in Indian populations." (PMID 19055786, 2008). "ICAM-1 is one of several cell adhesion molecules important in Plasmodium falciparum malaria." (PMID 20712868, 2010). "In severe falciparum malaria Ang-2 correlates with impaired endothelial function, lactate, plasma HRP2, ICAM-1, and E-selectin." (PMID 25569250, 2015). "The data highlights the significance of variations in the ICAM1, PECAM1 and CD36 genes in the manifestation of falciparum malaria in India." (PMID 19055786, 2008). "Median concentrations of Ang-2, E-selectin and ICAM1 were at least as high in severe and non-severe vivax malaria as they were in severe and non-severe falciparum malaria." (PMID 25569250, 2015). "Mutations in the human genes ICAM-1, CD36 and globin genes have been associated with susceptibility to severe falciparum malaria, in some but not all populations." (PMID 21390226, 2011).
glaucoma (8 papers, 2009 to 2025). Increased pressure in the eyeball due to obstruction of the outflow of aqueous humor. "ICAM-1 was identified to be produced by trabecular meshwork cells under oxidative stress which was a mechanism of glaucoma." (PMID 40463390, 2025). "Major membrane receptors affected in glaucoma included ICAM1 (up-regulated), PDGF-Rα and CCR1 (down-regulated)." (PMID 19426536, 2009). "In our study, highly expressed ICAM-1 was found in leukocytes of glaucoma patients; in contrast, only traces, if any, of the target expression was detected in the leukocytes of healthy controls." (PMID 19936302, 2009). "Consistent with mass spectrometry findings, we observed that A2M, B2M, Clusterin, TNC, FVII, Adiponectin, CRP, SAA, ICAM-1 and VCAM-1 were differentially affected in the retinas and vitreous of glaucoma subjects." (PMID 28978942, 2017). "ICAM-1 knockdown can suppress the apoptosis of TM cells induced by H2O2, which may reveal new therapeutic targets and biomarkers for glaucoma." (PMID 35562675, 2022).
glomerulonephritis (8 papers, 2010 to 2023). A renal disorder characterized by damage in the glomeruli. "The observed effects of unstimulated HSglx, LPS HSglx, fucoidan and sulodexide on cytokine mRNA and protein levels and ICAM-1 mRNA levels in LPS-induced glomerulonephritis can be attributed to both glomerular cells and immune cells." (PMID 37475889, 2023). "In summary, the inability of the compounds to attenuate the ICAM-1 protein expression in experimental glomerulonephritis is mirrored in the glomerular influx of granulocytes and monocytes." (PMID 37475889, 2023). "We then analysed the expression of ICAM‐1, involved in the progression of various types of glomerulonephritis, by leukocyte infiltration and macrophage accumulation." (PMID 32822114, 2020). "ICAM-1 expression is reported to be upregulated by CD44 and associated with leukocyte infiltration in human glomerulonephritis." (PMID 24595031, 2014). "In all patterns of glomerulonephritis the expression of ICAM-1 ranged from minimum to moderately severe and P-selectin from absent to severe." (PMID 20459816, 2010). "In all patterns of glomerulonephritis the expression of ICAM-1 was from minimum to moderate or severe intensity and P-selectin from absent to severe intensity." (PMID 20459816, 2010). "Although the unaffected influx of granulocytes and monocytes by any treatment was unexpected, it is in line with the unaltered glomerular ICAM-1 protein expression in the different treatment groups compared to the untreated LPS-induced glomerulonephritis group." (PMID 37475889, 2023). "ICAM‐1 expression is stimulated and increased by oxidative stress and TNF‐α and is associated with disease progression in several types of human and experimental glomerulonephritis." (PMID 32822114, 2020). "Expression of ICAM-1 was reported in certain human glomerulonephritis and in murine malaria." (PMID 20459816, 2010). "Both glomerular ICAM-1 and VCAM-1 protein expression were increased in mice with LPS-induced glomerulonephritis compared to control mice." (PMID 37475889, 2023). "Both ICAM-1 and VCAM-1 cortical mRNA expression showed a significant increase in LPS-induced glomerulonephritis compared to control mice." (PMID 37475889, 2023). "The observation that all treatments were able to alter cytokine and ICAM-1 mRNA expression levels in vivo but not in vitro suggest that the interplay between various cell types is crucial for the effect in experimental glomerulonephritis." (PMID 37475889, 2023). "Nevertheless, glomerular ICAM-1 protein expression in mice with LPS-induced glomerulonephritis mice was not affected by treatment with GAGs or Fucoidan." (PMID 37475889, 2023). "In intracellular adhesion molecule-1 (ICAM-1) knockout mice treated with TIM-1 antibody, the renal and spleen mRNA expressions of the Th1 chemokines CXCL9 and CXCL10 were reduced and ICAM-1 mediated the recruitment of leukocytes in glomerulonephritis." (PMID 33240910, 2020). "Both cortical ICAM-1 and VCAM-1 mRNA expression were increased in LPS-induced glomerulonephritis in our study while the four treatments could only reduce the ICAM-1 mRNA expression and not the VCAM-1 mRNA expression." (PMID 37475889, 2023).
migraine (8 papers, 2017 to 2025). "Elevated levels of soluble ICAM1 have also been detected in the internal jugular vein within two hours after migraine onset." (PMID 40699640, 2025). "In this study, we identified that NTG-induced migraine is associated with the PI3K–Akt signaling pathway, cytokines and their receptor interactions, and nine key hub genes (Alb, Tgfb1, Cd4, Ptprc, Itgb1, Icam1, Col1a1, Pxdn, and Itgad) through transcriptomics." (PMID 40699640, 2025). "Among them, Alb, Tgfb1, Icam1, CD4, and Ptprc are explicitly or potentially implicated in immune-inflammatory and oxidative stress mechanisms involved in migraine pathophysiology." (PMID 40699640, 2025). "ICAM1 expression is upregulated during migraine attacks and may contribute to aseptic dural neurogenic inflammation." (PMID 40699640, 2025). "In this study, transcriptomic analysis revealed significant downregulation of Alb and upregulation of Tgfb1, Icam1, CD4, and Ptprc in NTG-induced migraine model rats." (PMID 40699640, 2025). "Elevated levels of MMP-9 and ICAM-1 as well as endothelial cell-specific molecule-1 (ESM-1) and claudin-5 have been observed in migraine patients supporting the involvement of BBB disruption during attacks." (PMID 37596546, 2023). "Interestingly, elevated serum levels of ICAM1, a marker of vascular endothelial damage, have also been reported in migraines with aura compared to those with migraines without aura." (PMID 34444772, 2021).
Myocardial fibrosis (8 papers, 2012 to 2025). "Excessive ROS generation upregulates the expression levels of vascular adhesion molecules, particularly VCAM-1 and ICAM-1, facilitating myocardial infiltration by activated leukocytes, transformation of fibroblast into myofibroblasts, and the progression of myocardial fibrosis." (PMID 40429987, 2025). "The interaction of leukocytes with fibroblasts and myofibroblasts through the integrin/ICAM-1-dependent mechanism may promote extracellular matrix remodeling and myocardial fibrosis." (PMID 35493479, 2022). "MCC950 also reduced the levels of IL-1β, IL-18, vascular cell adhesion molecule 1 (VCAM-1), and intercellular adhesion molecule 1 (ICAM-1), alleviating myocardial fibrosis and infiltration of inflammatory cells." (PMID 40565074, 2025). "In a rat model of suprarenal aortic constriction, antibody blockade of either intercellular adhesion molecule-1 (ICAM-1) or MCP-1 reduced early macrophage recruitment, and prevented the development of myocardial fibrosis." (PMID 22916095, 2012). "Indeed, macrophage recruitment which is mediated in part by Mcp-1 and adhesion molecules such as intracellular adhesion molecule 1 (ICAM-1) and vascular cell adhesion molecule 1 (VCAM-1), exerts a crucial role in myocardial fibrosis and diastolic dysfunction." (PMID 24558494, 2014). "From molecular analyses, we concluded that the reverse process of myocardial fibrosis was dependent on upregulation of PPARα and PPARγ expression, downregulation of NF-κB expression, and suppressing TNF-α, ICAM-1, and MCP-1 production through the NF-κB signaling pathway." (PMID 24171042, 2013).
prediabetes (8 papers, 2011 to 2025). "In a cohort study that tested the likelihood of developing DM in prediabetic and normoglycemic individuals based on serum VCAM-1 and ICAM-1, individuals with prediabetes were found to have higher concentrations of these indicators than control individuals." (PMID 36983800, 2023). "Interestingly a trend has been recently identified in females (which does not appear to be present in males) for higher levels of not only E-selectin, but also ICAM-1 and PAI-1 in women prior to the development of prediabetes." (PMID 26196519, 2015). "Moreover, assessment of endothelial function in individuals with prediabetes, using well-established vascular (FMD, EndoPAT) and biochemical (ADMA, VCAM-1, ICAM-1) markers could add context in clinical practice." (PMID 36983800, 2023).
retinal ischemia (8 papers, 2009 to 2024). A ischemic disease that involves the retina. "Increased levels of ICAM-1 cause vascular endothelial damage with formation of acellular capillaries, which further leads to retinal ischemia and up regulation of VEGF." (PMID 31583119, 2019). "ICAM-1 increases in response to retinal ischemia, promoting leukocyte rolling and adhesion to vessel walls, resulting in leukostasis and blood stagnation." (PMID 39272767, 2024). "In support to our findings, cilostazol effectively reduced the expression of ICAM-1 and was able to suppress the leucocyte-endothelial cell interactions in an experimental model of retinal ischemia." (PMID 24816434, 2014). "The concentration of VEGF required to increase ICAM-1 in vitro was comparable to that measured in the vitreous of eyes with retinal ischemia and neovascularization." (PMID 23922493, 2013). "Immunohistochemistry and western blot analysis showed that the expression of ICAM-1 was obviously increased after retinal ischemia in this study which was compatible with other experiments which indicated that the ICAM-1 mRNA level increased obviously after retinal I/R injury." (PMID 26175842, 2015). "ICAM-1 is significantly elevated in both BRVO and CRVO and positively correlates with CRT, the height of serous retinal detachment, and the degree of retinal ischemia." (PMID 39272767, 2024).
subarachnoid hemorrhage (8 papers, 2013 to 2024). A serious neurological disorder characterized by intracranial hemorrhage into the subarachnoid space. "Elevated levels of sICAM1 have been reported in patients with subarachnoid hemorrhage, and thus further investigation into the role of ICAM1 in HHT-associated BAVM may yield useful insights." (PMID 34479577, 2021). "As a sign of local inflammatory response, the levels of E-selectin, VCAM-1, ICAM-1, and L-selectin were found to be elevated in the cerebrospinal fluid (CSF) of patients after subarachnoid hemorrhage." (PMID 32210955, 2020). "ICAM-1 is a potential therapeutic target to attenuate cerebral vasospasm after subarachnoid hemorrhage." (PMID 32210955, 2020). "In patients with subarachnoid hemorrhage, both ICAM-1 and VCAM-1 were increased in cerebrospinal fluid and serum." (PMID 28753621, 2017). "Previous studies have shown that acute intestinal injury caused by several neurological diseases, including traumatic brain injury and subarachnoid hemorrhage, upregulates ICAM-1 expression." (PMID 27929421, 2016). "Brain hemorrhage triggers a local inflammatory response, and consequently, the levels of soluble adhesion molecules (i.e., E-selectin, ICAM-1, VCAM-1, and L-selectin) and inflammatory cytokines are elevated in the CSF of patients after subarachnoid hemorrhage." (PMID 32210955, 2020).
ulcerative colitis (8 papers, 2015 to 2024). An inflammatory bowel disease involving the mucosal surface of the large intestine and rectum. "ICAM-1 was shown to be elevated in colon lysates collected from patients with ulcerative colitis." (PMID 34630738, 2021). "ICAM1 facilitates the transepithelial migration of neutrophils and their accumulation in the luminal surface of the intestine, which contributes to mucosal injury leading to conditions such as ulcerative colitis." (PMID 26303932, 2015). "In summary, the overexpression of H19 in MSC downregulated miR-139 and miR-141, thus increasing the activity of their targets ICAM-1 and CXCR4, respectively, to exhibit therapeutic effects in ulcerative colitis." (PMID 34630738, 2021). "Since it has been verified that the overexpression of ICAM-1 and CXCR4 can promote the homing of MSC in the treatment of ulcerative colitis, the overexpression of H19 exhibited therapeutic effects in ulcerative colitis." (PMID 34630738, 2021). "In humans, ICAM-1 has been found to increase in colonic lysates from ulcerative colitis patients compared to non-inflammatory controls." (PMID 38543230, 2024).